BICC1 (BicC family RNA binding protein 1)
Description:
Putative RNA-binding protein. Acts as a negative regulator of Wnt signaling. May be involved in regulating gene expression during embryonic development.
Synonyms: BICC
Tractability: PROTAC: ubiquitination databases record sites on it.
Gene: Protein-coding gene on chromosome 10 (58,512,872 to 58,831,435, forward strand). Ensembl gene ENSG00000122870.
Subcellular location: Cytoplasm
Subcellular location (Human Protein Atlas): Cytosol; Centrosome
Gene Ontology:
Molecular function: RNA binding; nucleic acid binding
Biological process: negative regulation of canonical Wnt signaling pathway; determination of left/right symmetry; mRNA catabolic process
Cellular component: cytoplasm
Genetic constraint (gnomAD): Loss-of-function variants: 35 observed, 85.74 expected, observed/expected ratio (o/e) 0.41, 90% interval 0.31 to 0.54. The upper end of that interval is the gene's LOEUF score, 0.54, which puts it in group 2 of 6, group 1 being the genes least tolerant of losing a copy. Missense variants: 958 observed, 1,069.5 expected, observed/expected ratio (o/e) 0.9, 90% interval 0.85 to 0.94. Synonymous variants: 417 observed, 395.32 expected, observed/expected ratio (o/e) 1.05, 90% interval 0.97 to 1.14.
Homologues: Orthologues: chimpanzee BICC1 (99% identical), macaque BICC1 (99% identical), pig BICC1 (97% identical), dog BICC1 (94% identical), mouse Bicc1 (93% identical), rat Bicc1 (93% identical), rabbit BICC1 (91% identical), guinea pig BICC1 (91% identical), tropical clawed frog bicc1 (83% identical), zebrafish bicc1a (63% identical), zebrafish bicc1b (42% identical). Paralogues in human: HDLBP (18% identical), ANKS6 (18% identical).
Diseases named in the same sentence as BICC1 in open-access papers:
BICC1 is named in the same sentence as 63 diseases in open-access papers, as found by Europe PMC text mining. Sharing a sentence is not in itself a finding about the gene and the disease. The quoted sentences say what the papers report.
cholangiocarcinoma (14 papers, 2016 to 2025). A carcinoma that arises from the intrahepatic biliary tree (intrahepatic cholangiocarcinoma) or from the junction, or adjacent to the junction, of the right and left hepatic ducts (hilar cholangiocarcinoma). "FGFR2 fusions occur in approximately 10–16% of cholangiocarcinomas, with common fusion partners including BICC1, AHCYL1, and PPHLN1." (PMID 41514604, 2025). "One of the most prevalent genome rearrangements that gives rise to cholangiocarcinomas is a fusion between the genes encoding FGFR2 (Fibroblast growth factor receptor 2) and BICC1 that results in the production of an FGFR2-Bicc1 fusion protein." (PMID 36158189, 2022). "In this technical report, we describe the generation of an endogenous FGFR2–Bicaudal family RNA binding protein 1 (BICC1) fusion in multiple independent cholangiocarcinoma and immortalized liver cell lines using CRISPR." (PMID 32252259, 2020). "The mRNA levels of BICC1 were increased in 10 cancers, such as pancreatic adenocarcinoma, glioblastoma multiforme, glioma, stomach adenocarcinoma, kidney renal papillary cell carcinoma, and cholangiocarcinoma." (PMID 37880742, 2023).
Renal cyst (11 papers, 2012 to 2023). A fluid filled sac in the kidney. "Renal cysts also associate with mutations in Bicaudal C1 (Bicc1) or in its self-polymerizing sterile alpha motif (SAM)." (PMID 29995892, 2018). "PKD-like cystic kidneys also develop in mice that lack the RNA-binding protein Bicaudal-C (Bicc1), and mutations in a single copy of human BICC1 associate with renal cystic dysplasia." (PMID 29995892, 2018). "Renal cysts also develop in mice and humans carrying mutations in the Bicc1 gene that encodes the cytoplasmic RNA-binding protein Bicaudal-C." (PMID 25888842, 2015). "Mutations in Bicc1 as well as in its Xenopus and zebrafish orthologs result in cystic kidneys." (PMID 28406902, 2017). "Bicc1 is an mRNA transporter protein, that when mutated results in renal cysts development." (PMID 28450740, 2017). "In model organisms mutations of mouse Bicc1 as well as morpholino disruption of Xenopus and zebrafish Bicc1 orthologs in developing embryos result in cystic kidneys that closely resemble the defects due to PKD." (PMID 36158189, 2022). "Drosophila BicC mutants develop with malformed Malpighian tubules that resemble the renal cysts found in vertebrates in which BICC1 expression is disrupted." (PMID 36158189, 2022). "More recently, Bicc1 was identified as a binding partner of the ankyrin repeat- and SAM domain-containing protein ANKS6, which is mutated in cystic kidneys of a subset of nephronophthisis patients." (PMID 29995892, 2018). "The Bicc1/Ank/NPHP complex was implicated in human nephronophtisis, a cystic kidney disease characterized by multiple extra-renal manifestations." (PMID 28406902, 2017). "Studies also link the RNA-binding protein bicaudal C homolog 1 (Bicc1) to renal cystic disease in patients and animal models." (PMID 28450740, 2017). "We show that Bicc1 mutant cystic kidneys fail to retain the protein and instead release it into urine." (PMID 25888842, 2015). "During AKI, Fetuin-A was enriched both in the cytoplasm of damaged proximal tubule cells and in urine, similar to what we observed in cystic kidneys of Bicc1 KO mice." (PMID 25888842, 2015). "The emergence of a protein network involving ANKS6, ANKS3 and BICC1 provides important clues on novel mechanisms involved in the formation of renal cysts." (PMID 26327442, 2015). "Large cystic kidneys showing hyperactivation of EGFR, Src and mTORC1 also develop in homozygous mutant bpk mutant mice owing to a frame-shifting mutation in one of two alternative transcripts of Bicc1." (PMID 29995892, 2018). "Interestingly, Ofd1 and Bicc1 are both involved in renal cystogenesis and selected targets were shown to accumulate in two models of inherited renal cystic disease." (PMID 28450740, 2017). "Moreover, a chemically induced point mutation in the SAM domain of ANKS6 that impairs its recruitment to Bicc1 in cystic kidneys of ANKS6I747N/I747N mice has been shown to diminish the accumulation of polycystin-2, a phenotype that is reminiscent of Bicc1 loss-of-function." (PMID 37733651, 2023). "Furthermore, a novel translation-activating function of Bicc1 mediated by binding to eIF3 on mRNAs specifically at centrosomes seems to require fine-tuning by the orofacial-digital syndrome protein-1 (OFD1) to suppress renal cyst formation." (PMID 29995892, 2018). "Bicc1 and the ankyrin and SAM domain proteins ANKS3 and ANKS6 all suppress renal cysts and can coprecipitate each other." (PMID 29995892, 2018). "Thus, besides being epistatic to PC1 and PC2, Bicc1 likely mediates multiple functions that could be relevant in PKD and other cystic kidney diseases." (PMID 29995892, 2018).
gastric cancer (8 papers, 2021 to 2025). A primary or metastatic malignant neoplasm involving the stomach. "BICC1 has been identified as a novel prognostic biomarker in gastric cancer, associated with immune infiltrates, and has also been suggested as a diagnostic marker for NAFLD." (PMID 38224712, 2023). "Putative RNA-binding protein BICC1 contributes to cell viability and is associated with poor prognosis among patients with oral and gastric cancers, consistent with proposed oncogenic role of BICC1." (PMID 34072264, 2021). "In addition, BICC1 was highly expressed in gastric cancer and significantly associated with tumor grade." (PMID 41197401, 2025). "Additionally, several factors contribute to the differential expression of BICC1 in gastric cancer, including other post‐translational modifications such as acetylation and transcriptional regulation." (PMID 39717922, 2025). "In addition, BICC1 expression was positively and strongly correlated with immune cells and macrophages in gastric cancer." (PMID 35578692, 2022).
pancreatic cancer (8 papers, 2023 to 2026). "BICC1 is also associated with lymph node metastasis in pancreatic cancer patients, and is enriched in the major EMT pathway, promoting tumor progression." (PMID 39717922, 2025). "In pancreatic cancer, BICC1 facilitates metastasis by binding to the mRNA of LCN2, thereby increasing LCN2 expression." (PMID 39717922, 2025). "In pancreatic cancer, BICC1 promoted resistance of pancreatic cancer to chemotherapeutic agents and increased the stemness character of the tumor." (PMID 39717922, 2025). "Hence, BICC1 emerges as a multifaceted regulator in pancreatic cancer, influencing processes such as EMT, immune infiltration, angiogenesis, chemoresistance and stemness." (PMID 40427100, 2025). "In pancreatic cancer, BICC1 was shown to facilitate angiogenesis in a VEGF-independent manner." (PMID 40427100, 2025). "Elevated BICC1 expression might affect immune cell infiltration and was shown to correlate with oncogenic pathways like EMT, TNFα/NF-kB and TGF-β signalling, which might underlie the poor prognosis of pancreatic cancer patients that express high levels of BICC1 in their tumours." (PMID 40427100, 2025). "The RNA‐binding protein BICC1 enhances chemoresistance in pancreatic cancer by upregulating IDO1 expression, suggesting that targeting the BICC1/IDO1/Trp metabolic axis could help overcome drug resistance." (PMID 41332472, 2025). "Through bioinformatics analysis, Meng and colleagues found that BICC1 was predominantly enriched in the EMT pathway and speculated that it plays a role in the lymphatic metastasis of pancreatic cancer." (PMID 39717922, 2025). "While no direct evidence regarding BICC1 and CRC has been reported, BICC1 has been found to drive pancreatic cancer progression via inducing VEGF-independent angiogenesis and might serve as a promising anti-angiogenic therapeutic target." (PMID 41197401, 2025).
depression (7 papers, 2016 to 2025). "Genetic studies further support this link, with two single nucleotide polymorphisms (SNPs) in the BICC1 gene associated with depression." (PMID 41340853, 2025). "BICC1 has been identified by GWAS as a candidate gene associated with major depressive disorder in humans." (PMID 31561612, 2019). "There are recent genome-wide association studies (GWAS) that have associated BICC1 with depression, bone mineral density and muscle mass." (PMID 31513639, 2019). "Depression-associated single-nucleotide polymorphisms can regulate the expression of the bicaudal C homolog 1 (BICC1) gene and decrease its promoter activity on the PKA signaling pathway in amygdalar neurons." (PMID 28246558, 2017). "Correlative studies of human BICC1 along with experimental investigations in rodent models have revealed potential links between the Bicc1 activity in specific neurons of the brain and severe depression." (PMID 36158189, 2022). "Previous studies reported the association of BICC1 with POAG, major depressive disorder, and high myopia." (PMID 35741817, 2022). "To locate the presence of a human genomic locus that could contribute to susceptibility to major depressive disorder we carried out a GWA analysis of a large patient cohort and succeeded in identifying two SNPs within intron 3 of the BICC1 gene with significant association." (PMID 26440730, 2016).
oral cancer (7 papers, 2021 to 2025). "Researchers have discovered that BICC1 is highly expressed in oral cancer, where it promotes tumor growth by enhancing cell survival and preventing apoptosis." (PMID 39717922, 2025). "For instance, miR‐101‐3p and miR‐199b‐5p promote apoptosis in oral cancer cells by targeting and inhibiting BICC1 expression." (PMID 39717922, 2025). "The findings suggest that tumor cells are stimulated by BICC1 by inhibiting apoptosis, which leads to a lower survival rate for people with oral cancer." (PMID 37880742, 2023). "In oral cancer, the increased level of miR-101 promotes apoptosis by suppressing BicC family RNA binding protein 1 (BICC1)." (PMID 36497343, 2022). "MiR-101-3p promotes apoptosis of oral cancer cells by targeting BICC1, induces dysfunction of vascular endothelial cell by targeting tet methylcytosine dioxygenase 2, suppresses proliferation and metastasis of glioblastoma cells via targeting TRIM44." (PMID 34977016, 2021). "In addition, some studies also found that BICC1’s aberrant expression contributes to the development of other malignant tumors: oral cancer, Wilms tumor and non-small cell lung cancer." (PMID 37880742, 2023). "miR-101-3p can advance the apoptosis of oral cancer cells by targeting BICC1." (PMID 34307682, 2021).
myopia (4 papers, 2018 to 2024). "A recent study indicated that genetic variants in BICC1 and RASGRF1 are closely associated with high myopia, which appears to be a potential candidate for high myopia in a Chinese Han population." (PMID 29576878, 2018). "Researchers indicate that PAX6 rs644242, ZC3H11B rs4373767 and BICC1 rs7084402, VIPR2 rs885863 and rs6979985, ZMAT4 rs7829127, TNKS rs4840437 and rs6989782, PDGFRA rs2114039, SOX2 rs4575941, FGF10 rs339501, rs2973644, and rs 79002828 are associated with severe myopia (moderate and extreme myopia)." (PMID 38660258, 2024).
polycystic kidney disease (4 papers, 2014 to 2022). A usually autosomal dominant and less frequently autosomal recessive genetic disorder characterized by the presence of numerous cysts in the kidneys leading to end-stage renal failure. "Although Bicc1 mutations in these models result from different mutant Bicc1 proteins, all the models exhibit cystic phenotypes in the kidney that are very similar to human polycystic kidney disease." (PMID 24594709, 2014). "Targeted mutations of mouse Bicc1 as well as morpholino disruption of Xenopus and zebrafish Bicc1 orthologs in developing embryos all result in abnormal kidneys that closely resemble defects due to polycystic kidney disease (PKD)." (PMID 36158189, 2022). "BICC1 is involved in osteoblastogenesis and polycystic kidney disease, in part, through its inhibition of posttranscriptional silencing of PKD2 RNA by miR‐17." (PMID 33977200, 2021). "Studies using chemically-induced or natively occurring Bicc1-mutant mouse models (jcpk and bpk) and other Bicc1-gene-targeted mouse models have recently demonstrated that the disruption of Bicc1 can induce polycystic kidney disease with phenotypes very similar to human ADPKD." (PMID 24594709, 2014). "In contrast to the early work done in Drosophila, Bicc1 did not impact the poly(A) tail of Adcy6 target mRNA in a mouse model of polycystic kidney disease." (PMID 36158189, 2022).
breast carcinoma (3 papers, 2017 to 2021). "Fusion partners of FGFR2 reported specifically in breast cancer are AFF3, CASP7 and CCDC6, while partners identified in other cancers include TACC and KIAA family members, PPHLN1, NTRK1, BICC1, AHCYL1, OFD1 and SLC45A3." (PMID 34344433, 2021).
intrahepatic cholangiocarcinoma (3 papers, 2020 to 2021). A carcinoma that arises from the intrahepatic bile duct epithelium in any site of the intrahepatic biliary tree. "About 45% of the intrahepatic cholangiocarcinoma cases are coupled with FGFR2 fusion, half of which are with bicaudal C1 (BICC1); identification of FGFR2-BICC1 in other types of cancer is rare." (PMID 34207779, 2021).
Cardiomyopathies (2 papers, 2024 to 2025). "These disorders are categorized into major clinical groups, such as Skeletal Dysplasias (e.g., analysis of genes like ACAN, ACP5, and ACVR1), Osteogenesis Imperfecta (COL1A1, COL1A2, BMP1), Metabolic Disorders (ACE, AGT, BICC1), and Cardiomyopathies, among others." (PMID 40282387, 2025).
ciliopathy (2 papers, 2016 to 2023). A genetic disorder of the cellular cilia or the cilia anchoring structures, the basal bodies, or of ciliary function. "The dual regulation of RNA binding by mutually opposing structured protein domains in this multivalent protein network emerges as a novel mechanism linking associated laterality defects and possibly other ciliopathies to perturbed dynamics in Bicc1 ribonucleoparticle (RNP) formation." (PMID 37733651, 2023). "Structure-function analysis of the ciliopathy proteins ANKS3 and ANKS6 suggests a dual role in either inhibiting or promoting the binding of Bicc1 to its own transcripts and to client mRNAs." (PMID 37733651, 2023).
colon cancer (2 papers, 2025). "BICC1, an RNA-binding protein, influences tumor progression in colon cancer through pathways such as extracellular matrix (ECM) receptor interaction and focal adhesion." (PMID 41132793, 2025). "Of them, 10 aging-related CpG sites were mapped to 6 genes (i.e., TNF, BICC1, TBX3, SUCNR1, NCF2, DIP2B), and the altered methylation of cg03037030 located in TNF was associated with the risk of CRC, colon cancer, and rectal cancer, with consistent effect direction." (PMID 41197401, 2025).
lung carcinoma (2 papers, 2021 to 2022). "To further validate these novel players in lung cancer cell migration, we selected five candidates—DSE, CPA4, FLNC, TUBB6, and BICC1—and the positive control CDH2, which were upregulated in fast cells and also associated with poor overall survival in NSCLC patients." (PMID 33934493, 2021).
osteoporosis (2 papers, 2021 to 2022). A condition of reduced bone mass, with decreased cortical thickness and a decrease in the number and size of the trabeculae of cancellous bone (but normal chemical composition), resulting in increased fracture incidence. "Further support for the biological relevance of several or more of these Tier‐1 SNPs to osteoporosis is that all seven TFs or families of TFs are predicted to bind in an allele‐specific manner to the five BICC1 Tier‐1 SNPs were related to the skeletal system." (PMID 33977200, 2021). "In 2021, the five priority osteoporosis genes were discovered from 38 reported BMD genome-wide association studies (GWAS), with Bicc1 having the highest Tier-1 SNPs, indicating that Bicc1 was a crucial gene in controlling osteoporosis." (PMID 35756494, 2022). "The purpose of this study is to explore the probable function of BICC1 in osteoporosis and osteogenic differentiation of aged BMSCs." (PMID 35756494, 2022). "Primary cilia containing PKD2/PC2 and PKD1/PC1 operate as osteoporosis-related mechanoreceptors in osteoblasts and renal epithelial cells, and BICC1 has been found in renal cell primary cilia." (PMID 35756494, 2022). "As a result, more research was required to uncover the potential regulatory mechanisms of BICC1 in elderly osteoporosis." (PMID 35756494, 2022). "As a genetic gene that affects bone mineral density, BICC1 may be a new target for clinical treatment of senile osteoporosis by influencing osteogenic differentiation of BMSCs through EGFR-related signaling." (PMID 35756494, 2022). "There is currently a lack of comprehensive evaluation of the effect of BICC1 on osteoporosis and osteogenic differentiation of aged BMSCs." (PMID 35756494, 2022).
Pancreatic cysts (2 papers, 2019 to 2022). A cyst of the pancreas that possess a lining of mucous epithelium. "BICC1 provokes renal and pancreatic cysts and the visceral left-right patterning of ectopic Wnt/β-catenin signaling during visceral left-right patterning." (PMID 31561612, 2019). "Additionally, comparison of mRNA changes in pancreatic cells between WT and Bicc1 knockouts indicated that Pkd2 functions downstream of Bicc1 in preventing pancreatic cyst formation." (PMID 36158189, 2022).
renal cystic dysplasia (2 papers, 2017 to 2018). "Maintaining normal Bicc1 expression is likely important since mutation or loss of a single copy of BICC1 in human is sufficient to provoke renal cystic dysplasia." (PMID 29995892, 2018).
autosomal dominant polycystic kidney disease (1 paper, 2014). Autosomal dominant form of polycystic kidney disease. "In addition, we discovered that loss of the Pkd1 gene product, polycystin-1 (PC1), whose mutation causes human autosomal dominant polycystic kidney disease (ADPKD), downregulates Bicc1 expression in vitro and in vivo." (PMID 24594709, 2014).